FGFR1 (fibroblast growth factor receptor 1)
Diseases named in the same sentence as FGFR1 in open-access papers (continued):
Sharing a sentence is not in itself a finding about the gene and the disease.
cancer (continued). "Earlier studies reported FGFR1 as a potential drug target in many human cancers." (PMID 32617189, 2020). "Our data, besides fundamental importance for FGFR1 biology, might be relevant for the design of highly efficient targeting molecules for ADC therapy of FGFR1‐overproducing cancers." (PMID 32511887, 2020). "Tetravalent antibody‐mediated FGFR1 clustering largely improves the uptake efficiency, which may boost the selective delivery of drugs into FGFR1‐overproducing cancer cells." (PMID 32511887, 2020). "We, thus, investigated whether the decreased drug availability also results in decreased inhibitory potential of ponatinib on its target kinases (e.g., FGFR1) in cancer cells." (PMID 32064608, 2020). "FGFR1 has been demonstrated as an oncogene in a series of cancers." (PMID 33000910, 2020). "FGFR1 has been known to be related to the prognosis of several human cancers." (PMID 32171280, 2020). "The expression pattern of FGFR1-4 varied a lot among all the cancer types." (PMID 32596330, 2020). "To gain further insight into the interaction between miR-198 and FGFR1, we next examined if FGFR1 overexpression, mediated by transfection of pCDNA3.1-FGFR1, could abrogate the cancer-suppressive effects of miR-198." (PMID 31138759, 2019). "The tyrosine kinases involved in the Y10 phosphorylation of LDHA are HER2, the avian sarcoma viral oncogene v-src homolog (Src) and the Fibroblast growth factor receptor 1 (FGFR1), this phosphorylation promotes the Warburg effect and pro-invasive and pro-metastatic potential of cancer cells." (PMID 31737570, 2019). "The activation of FGFR1 regulate the EMT in cancer progression." (PMID 30867653, 2019). "These evidences prompted the use of FGFR1 as a therapeutic target for the treatment of cancers." (PMID 31138759, 2019). "Therefore, combination of blocking FGFR1 signals with other anti-cancer drugs shall be a promising novel strategy for treating CRPC and other cancers with ectopic FGFR1 expression." (PMID 30761180, 2019). "FGFR1 gene amplifications have been studied in other cancers as well." (PMID 31754359, 2019). "Importantly, mesenchymal-like cancer cells expressed FGFR1(IIIc), whereas epithelial-like cancer cells expressed FGFR2(IIIb)." (PMID 31682640, 2019). "FGFR1 expression is regulated by the stem-cell associated transcription factor ZEB1, suggesting that FGFR1 may be associated with GBM cancer stem cells." (PMID 31337028, 2019). "Our data suggest, that extracellular galectins may directly activate FGFR1 to fuel cancer cell division and survival." (PMID 31208421, 2019). "Additionally, epithelial–mesenchymal transition (EMT), an important process for cancer dissemination and metastasis, is also induced by FGFR1 activation." (PMID 31138759, 2019). "In order to further confirm whether compound 15c can impede the phosphorylation of EGFR and FGFR1 in cells, the kinase inhibitory activity of 15c was detected in various ligand stimulated cancer cells." (PMID 31998131, 2019). "Due to the diversified mode of action the dual warhead-FGF2 conjugate may overcome the potential acquired resistance of FGFR1-overproducing cancer cells towards single cytotoxic drugs." (PMID 30029518, 2018). "The nuclear FGFR1 arises from the proteolytic processing of the full-length receptor by granzyme B. Importantly, the synthetic peptide inhibitor specific towards granzyme B blocked FGFR1 processing, nuclear translocation, and the migration of cancer cells." (PMID 30577533, 2018). "In addition, based on our previous studies on the FGFR24,25, we decided to develop novel pharmacophore-based inhibitors for treating FGFR1-driven cancers using a hybridisation strategy." (PMID 29734851, 2018). "In the mitochondria of cancer cells, FGFR1 promotes the Warburg effect by phosphorylating PDHK1." (PMID 30577533, 2018). "The FGFR tyrosine kinase family with FGFR1/2/3/4 plays important roles in cancer." (PMID 30111373, 2018).
cancer (continued). "Thus, the FGFR1-specific scFvD2-Fc antibody alone has a therapeutic potential, as it is able to decrease the FGFR1 levels on the cancer cell surface by inducing the cellular trafficking-dependent lysosomal degradation of the receptor." (PMID 30577533, 2018). "Taken together, our results suggested that compound C9 is a highly selective FGFR1 inhibitor with a novel chemical scaffold that may serve as a potential agent for further drug development in FGFR1-driven cancer therapy." (PMID 29734851, 2018). "Our data may facilitate design of therapeutically relevant targeting molecules for selective treatment of FGFR1 overproducing cancers." (PMID 29748524, 2018). "If FGFR1 has already been involved in resistance to other therapy as hormone therapy or targeted drugs in different cancer models, little is known concerning its role in cancer stem cells response to therapy." (PMID 30167084, 2018). "In numerous cancer cell types, the level of FGFR1 is elevated in comparison to the normal cells that may ensure selectivity of drug targeting." (PMID 29748524, 2018). "In summary, we propose the following mode of action for FGF2 dual warhead conjugate: The conjugate recognizes elevated levels of FGFR1 on the surface of cancer cells and utilizing receptor-mediated endocytosis it is targeted into lysosomes, degraded releasing α-amanitin and MMAE." (PMID 30029518, 2018). "Importantly, mitochondrial FGFR1 promotes the growth of cancer cells by adjusting the energy metabolism." (PMID 30577533, 2018). "Numerous tumors overproduce FGFR1, making this receptor a perspective target for cancer therapies." (PMID 29748524, 2018). "Robust responses to FGFR inhibition are seen only in high-level FGFR1-amplified cancers." (PMID 30140389, 2018). "All together our results demonstrate that inhibition of FGFR1 signaling in SQCLC cell lines may impact on cancer cell growth also by affecting glucose energy metabolism." (PMID 29190880, 2017). "As FGF2-FGFR1 signaling is critical for API5-mediated phenotypes of cancer cells, we reasoned that inhibition of FGFR1 signaling may serve as an effective strategy for targeting cancer cells, which highly express API5." (PMID 28092370, 2017). "FGFR1 low amplification was defined by ≥ 5 FGFR1 signals in ≥ 50% of cancer cells." (PMID 29088806, 2017). "FGFR1 amplification has been documented in ESCC and other cancer types; however, it still remains controversial whether FGFR1 amplification adversely impacts on the clinical outcome of ESCC patients." (PMID 29179482, 2017). "Previous studies found that phosphorylation of LDHA and PDHK1 by FGFR1 was common in diverse cancers which could activate LDHA and PDHK1 and promote glycolysis." (PMID 29132384, 2017). "Our data indicate that it may be beneficial to assess PDGFRα and FGFR1 levels to determine if ponatinib has similar efficacy in these cancers." (PMID 27783942, 2016). "Of interest, FGFR1 expression was also related to cancers with neuroendocrine differentiation." (PMID 26673008, 2016). "Our data showing poor outcome of FGFR1 expressing Lum A cancers may implicate the poor prognostication also for this Chr8-associated subgroup." (PMID 26673008, 2016). "FGFR1 expressing luminal A cancers showed a similar outcome as luminal B cancers." (PMID 26673008, 2016). "We found that FGFR1 expression was predominantly in luminal cancers, in particularly Lum B cancers." (PMID 26673008, 2016). "However, cancer cell lines with FGFR1 amplification have been shown to be sensitive to an FGFR inhibitor (NVP-BGJ398)." (PMID 27685995, 2016). "FGFR1 expression was associated with higher pN (p = 0.023), pT (p = 0.003) stages, lymphovascular invasion (p = 0.010), p-cadherin (p = 0.028), synaptophysin (p = 0.009) and SOX2 expression (p = 0.034) in luminal A cancers." (PMID 26673008, 2016). "In addition, recent studies have demonstrated that both full-length and truncated forms of FGFR1 accumulate in cancer cells and thereby promote metastasis." (PMID 25923916, 2015).
cancer (continued). "In addition, FGFR1 activation promotes the epithelial-mesenchymal transition (EMT) in several human cancers." (PMID 25760077, 2015). "Importantly, FGFR1 protein was relatively overexpressed in all cancer cells tested as compared with normal cells." (PMID 26201468, 2015). "Moreover, the important roles of FGFR1/ERK signal in a variety of cancers make it a potential therapeutic target for cancer therapy." (PMID 25760077, 2015). "Indeed, ARPCA hampers the capacity of FGF8b to form FGFR1-mediated ternary complexes with HSPGs, thus inhibiting FGFR1 activation and signalling triggered by FGF8b in endothelial and cancer cells." (PMID 25912421, 2015). "Further, N-cadherin, which was reported to promote cancer cell invasion and metastasis in association with FGFR1 and fibroblasts, was also excluded as not expressed in these cancer cells (data not shown)." (PMID 25973543, 2015). "Upon effective blockade of nuclear FGFR1 signalling, we can abolish cancer cell invasion." (PMID 24503018, 2014). "Furthermore, flexibility of the organotypic system allowed us to use PSCs that had been treated with FGFR1 RNAi to demonstrate that this regulation of stellate cell invasion, and modulation of cancer cell behaviour, is specific to FGFR1." (PMID 24503018, 2014). "Furthermore, CNAs, as often reported in clinical samples, were detected in the regions of some cancer-related genes; for example, copy number gains of FGFR1, EGFR and PDGFRA in H1703, amplification of MYC and a homozygous loss of CDKN2A in LC2/ad." (PMID 25378332, 2014). "FGFR1 may thus function as a survival factor for afatinib-resistant cancer cells, and activation of the FGFR-driven bypass signaling pathway confer resistance to previously effective therapy." (PMID 25115383, 2014). "Together, enhanced expression of FGFR1 and FGF2 thus plays as an escape mechanism for cell survival of afatinib-resistant cancer cells, that may compensate the loss of EGFR-driven signaling pathway." (PMID 25115383, 2014). "FGFR1 is one of the most commonly amplified genes in human cancer." (PMID 25171497, 2014). "Ligand binding leads to FGFR1 dimerization, autophosphorylation, and activation of signaling components including Akt and Erk kinases, further affecting malignant transformation of cancer cells." (PMID 25115383, 2014). "Indeed, we observe that FGFR1, 2, and 4 can all interact with TAK1, and overactivation of all has been associated with various human cancers, including those of the breast, lung, colon, endometrium, and prostate." (PMID 24466111, 2014). "Recently, in accord with our findings, Turner and colleagues reported that FGFR1 signaling suppressed PR expression and that FGFR1-amplified cancers had higher Ki-67 proliferation indices and were most often found in the luminal B subtype, accounting for 16 to 27% of their series." (PMID 22863309, 2012). "The efficacy of anti-FGFR-1 inhibitor is increasing also in carcinomas arising from other organs." (PMID 23270564, 2012). "The predictive biomarker may be assessed on metastatic tissue or in primary carcinomas, and the predictiveness to anti-FGFR-1 inhibitor is prone to be similar." (PMID 23270564, 2012). "FGFR1 has seven alternative promoters supported by curated full-length c-DNA clones, and at least of four of them have been shown to control the differential expression in a tissue- and cancer cell- specific manner." (PMID 20208995, 2010). "Similarly, FGFR2 product was also much less in cancer tissues (P = 0.0078), as was FGFR1 (P = 0.002)." (PMID 1380281, 1992). "Consequently, targeting FGFR1 for cancer therapy has become an appealing therapeutic strategy." (PMID 40934169, 2025). "However, broader kinase inhibition by R406 may impact pathways regulated by FGFR1, particularly in cancer, fibrosis, or tissue regeneration contexts." (PMID 41226200, 2025). "Additionally, these results suggest that FGF1-PIGN may be effective in the treatment of cancers expressing high levels of FGFR1." (PMID 38637316, 2024).
cancer (continued). "The expression levels of FGF receptors (FGFRs), particularly FGFR1 and FGFR2, significantly differ between carcinoma and para-carcinoma tissues in colon, gastric, and esophageal cancers, implicating their role in the susceptibility and progression of these cancers." (PMID 39691707, 2024). "Besides, four sex-biased exon skipping events in cancer therapeutic target genes (FDPS, FGFR1, CDK4, and IMPDH2) could cause the loss of partial protein function, which may contribute to a differential drug response rate in male and female patients." (PMID 39175079, 2024). "The tail-to-tail rearrangement upstream of FGFR1 had a 3-fold higher coverage of reads across the breakpoint compared with the rearrangement within FGFR1 (54 vs. 15 break-detecting reads), suggesting the second event had occurred later in the cancer genome evolution." (PMID 37606995, 2023). "Combined with the tumors with amino-terminal truncation of FGFR1, the carcinomas with tail-to-tail rearrangements within FGFR1 or in close proximity to the FGFR1 gene locus may thus constitute the overall population of FGFR1-dependent SQLC with sensitivity to FGFR inhibition." (PMID 37606995, 2023). "However, the differential role of FGFR1 expression has been observed in cancers." (PMID 35683481, 2022). "The seven prevalent ‘candidate genes’ (ADAM10, ADAM17, AKT1, CTNNB1, ESR1, FGFR1, PIK3CA) showed direct associations with enriched terms under the categories of ‘Neurodegenerative disorders’, ‘Neurodevelopmental diseases’, ‘CNS tumour/cancer’ and ‘Cellular Signaling pathways’." (PMID 36229517, 2022). "However, peptibodyC19 contains, in addition, two cysteine residuesin the targeting peptide sequence, which covalently modified withthe drug could result in decreased affinity for the FGFR1 and lessefficient delivery of the cytotoxic payload to cancer cells." (PMID 35389227, 2022). "Moreover, FGFR1 participated in the regulation of chemosensitivity in several cancers." (PMID 34899853, 2021). "Thus, the oligomeric targeting proteins within the conjugates may, by controlling the arrangement of FGFR1 on the cell surface, upregulate internalization of the receptor-conjugate complex, improving drug delivery to the cancer cells." (PMID 34635096, 2021). "Importantly, the q-arm carries several cancer-relevant genes such as FGFR1, KAT6A and PCM1." (PMID 34707142, 2021). "Therefore, FGFR1 overexpression may be used as a marker of tumorigenesis and inflammation and as a poor prognostic indicator of cancer patients." (PMID 33989301, 2021). "Thus, our data suggested that the T-Fc may constitute a highly efficient drug delivery vehicle for selective treatment of FGFR1-dependent cancers using ADC approach." (PMID 33962559, 2021). "The physiological significance of galectin‐3/FGFR1 interplay is currently unknown,however, the high‐affinity tetravalent antibody described in this study can be used to partially uncouple galectin‐3/FGFR1 interaction, which may be of potential relevance for therapeutic purposes in cancer treatment." (PMID 32511887, 2020). "Therefore, FGFR1 is an attractive molecular target for selective cancer treatment." (PMID 32511887, 2020). "Furthermore, it has been demonstrated that inhibition of FGFR1 signaling in SQCLC cell lines may also have an impact on cancer cell growth by affecting glucose energy metabolism." (PMID 31940827, 2020). "Thus, N-cadherin may promote invasiveness of cancer cells not only by regulating cell-cell interactions, but also by affecting FGFR1 levels and activity." (PMID 31091809, 2019). "Therefore, cyclic peptide F8 can act as a FGF1–FGFR1 interaction antagonist, and may be suitable for further development for potential use in therapies against FGFR1‐expressing cancer cells." (PMID 30968602, 2019). "Notch, ERBB2, and FGFR1 signaling pathway might be potential therapeutic targets to improve the outcome of CRC patients without germline cancer-associated genetic variants in adjuvant setting." (PMID 30850667, 2019).
cancer (continued). "To date, the major group of drugs being developed for treatment of FGFR1‐dependent cancers are small‐molecule tyrosine kinase inhibitors; however, the limited specificity of these drugs has led to increasing attempts to design molecules targeting the extracellular domain of FGFR1." (PMID 30968602, 2019). "Moreover, the authors proved that treatment with an FGFR1 inhibitor (PD173074) caused a loss of the cell lines’ ability to form colonies, suggesting that FGFR1 has a role in making those cancer cells capable of growing colonies, and therefore confirming its tumorigenic function in BC." (PMID 30011957, 2018). "Nevertheless, we note that if a normal function of FGFR1 signaling is to inhibit proliferation of wild-type airway BCs, then it is possible that administration of FGFR1-specific inhibitors as a cancer therapy may lead to clonal expansion of other pre-malignant cells." (PMID 27046834, 2016). "Thus FGFR1 could be useful in identifying the aggressive cases amongst heterogeneous luminal A cancers." (PMID 26673008, 2016). "Therefore, FGFR signaling might be a potentially promising therapeutic target in cancers exhibiting FGFR1 overexpression." (PMID 26581390, 2015). "Several receptor (EGFR, IGFR1, FGFR1...) and non-receptor (Abl) kinases have been selected, as well as serine/threonine/lipid kinases (AurA, Akt, CDKs, MAPKs...) implicated in main cancer pathways: cell cycle regulation, signal transduction, angiogenesis regulation among them." (PMID 21796074, 2011). "Compared to primary cancer, ABL1(0.3% vs 3.0%, p=0.007) and FGFR1 (7.1% vs 13.1%, p=0.016) were more likely to be observed in R/M sites." (PMID 40182039, 2025). "Compounds 13f, 19e, and 22f demonstrated potent inhibition of FGFR1-4 and dose-dependent suppression of FGFR1-mediated signaling, with strong antiproliferative activity in both FGFR-driven and wild-type cancer models." (PMID 41304987, 2025). "FGFR inhibitors have been tested in clinical trials to treat aggressive cancers harboring alterations in FGFR genes, including cases with FGFR1 alterations, with only partial responses and in some cases severe adverse events." (PMID 41174249, 2025). "Based on the ALAN quantitative outputs, RSPO2 behaved similarly to EMT-related genes and FGFR1/2, but exhibited opposing behavior with AR regulatory genes and MYC, a pan-cancer oncogene." (PMID 40711886, 2025). "This growth factor exerts its effects through interaction with fibroblast growth factor receptor 1 (FGFR1), promoting cancer cell migration and invasion, as well as stimulating the expression of Cyclin D1." (PMID 40725022, 2025). "Blocking this interaction, such as with the IMB-R1 antibody that specifically targets the heparin-binding domain of FGFR1, has been shown to inhibit FGF2-induced cell growth and induce apoptosis in cancer cells." (PMID 41226200, 2025). "Compared to the control cell line,eFGF1-161Tb showed much higher uptake and significantlyenhanced cytotoxicity on both FGFR1 and FGFR4 overexpressing celllines, which suggests that eFGF1-161Tb is a promising candidatefor targeted cancer therapy." (PMID 39989790, 2025). "PD173074 is a potent inhibitor of FGFR1 and VEGFR, and it was also shown to effectively resensitize chemoresistant cancer cells overexpressing ABCB1 and ABCC10 to some chemotherapeutic agents, including paclitaxel." (PMID 41154409, 2025). "To make a vector suitable for targeting cancer cells overexpressingFGFRs, we generated an engineered version of the FGF1 protein, a naturalligand for all four human FGFRs (FGFR1-4)." (PMID 39989790, 2025). "When FGFR1 is amplified, JAK-STAT with CBP/p300 as a potential coactivator is activated, which inhibits cancer progression through p21 upregulation." (PMID 38553760, 2024). "The aim was to examine the relationship between FGF2 and FGFR1 and their impact on mRNA expression of P21 and CCND1, cell cycle status, and cancer stemness characteristics." (PMID 38553760, 2024).